THRIL (TNF and HNRNPL related immunoregulatory long non-coding RNA)
Synonyms: Linc1992; TCONS_00020260; BRI3BP-AS1; BRI3BPAS1
Gene: Long non-coding RNA gene on chromosome 12 (125,025,434 to 125,027,410, reverse strand). Ensembl gene ENSG00000280634.
Diseases named in the same sentence as THRIL in open-access papers:
THRIL is named in the same sentence as 50 diseases in open-access papers, as found by Europe PMC text mining. Sharing a sentence is not in itself a finding about the gene and the disease. The quoted sentences say what the papers report.
Sepsis (6 papers, 2019 to 2023). Sepsis is defined as life-threatening organ dysfunction caused by a dysregulated host response to infection. "Additionally, the association of lnc‐THRIL with mortality in sepsis patients was assessed, which exhibited that lnc‐THRIL was upregulated in non‐survivors compared with survivors and was of good value in predicting mortality." (PMID 31257645, 2019). "Therefore, we speculated that lnc‐THRIL might increase the mortality in sepsis patients not only via raising the risk of ARDS, but also through other means, which needed to be further investigated." (PMID 31257645, 2019). "Our future studies will explore the effects of sepsis-related complications on the expression of THRIL." (PMID 32944003, 2020). "Compared to the control group, significantly upregulated THRIL was observed in sepsis patients (p < 0.05)." (PMID 32944003, 2020). "The following subgroup analysis further validated the predictive value of lnc‐THRIL on mortality in sepsis patients." (PMID 31257645, 2019). "ROC curve illustrated that lnc‐THRIL was of good value in distinguishing ARDS from non‐ARDS in sepsis patients with AUC of 0.706 (95%CI: 0.602‐0.809)." (PMID 31257645, 2019). "The positive correlation of lnc‐THRIL with inflammation in sepsis patients was verified in our following analysis." (PMID 31257645, 2019). "Thus, we hypothesized that lnc‐THRIL might participate in the pathogenesis of sepsis and contribute to ARDS risk in sepsis patients as well, and we aimed to investigate the correlation of lnc‐THRIL with the risk of ARDS, disease severity, inflammation as well as mortality in sepsis patients." (PMID 31257645, 2019). "In conclusion, lnc‐THRIL predicts increased risk of ARDS and positively correlates with disease severity, inflammation, and mortality in sepsis patients." (PMID 31257645, 2019). "Regarding inflammation, lnc‐THRIL was positively associated with CRP, PCT, TNF‐α, and IL‐1β levels in sepsis patients." (PMID 31257645, 2019). "Lnc‐THRIL predicts increased risk of ARDS and positively correlates with disease severity, inflammation, and mortality in sepsis patients." (PMID 31257645, 2019). "In acute lung damage led by sepsis, THRIL is upregulated, reflecting THRIL may be involved in lung injury." (PMID 37582734, 2023). "Another study on 109 patients with sepsis reported upregulation of lncRNA THRIL in ARDS group compared with non‐ARDS group; moreover, it could effectively distinguish between patients with and without ARDS (AUC: 0.706)." (PMID 34055659, 2021). "Moreover, lncRNA THRIL positively correlated with sepsis severity and also presented a good predictive value (AUC: 0.780) for mortality in patients with sepsis." (PMID 34055659, 2021). "We found that THRIL was upregulated in sepsis and may upregulate TNF-α by sponging miR-19a to promote cell apoptosis induced by LPS." (PMID 32944003, 2020). "In conclusion, THRIL is upregulated in sepsis and may sponge miR-19a to upregulate TNF-α, thereby promoting cell apoptosis induced by LPS." (PMID 32944003, 2020). "This study aimed to explore the role of THRIL, an enhancer of LPS-induced inflammatory, in sepsis." (PMID 32944003, 2020). "In another study, THRIL was demonstrated to increase the risk of acute respiratory distress syndrome (ARDS) and was positively correlated with inflammatory responses, disease severity and mortality in sepsis patients." (PMID 32944003, 2020). "Additionally, the mortality rate was 30.2%, and lnc‐THRIL was upregulated in non‐survivors compared with survivors, presenting a good value (AUC: 0.780; 95%CI: 0.683‐0.876) in predicting mortality in sepsis patients." (PMID 31257645, 2019). "Lnc‐THRIL relative expression was elevated in non‐survivors (4.262 [1.983‐5.582]) compared with survivors (1.784 [0.928‐2.849]), and it presented a great value in predicting mortality in sepsis patients with AUC of 0.780 (95%CI: 0.683‐0.876)." (PMID 31257645, 2019).
Sepsis (continued). "Multivariate logistic regression further disclosed that lnc‐THRIL relative expression (OR = 1.511, P = 0.034), smoke (OR = 3.983, P = 0.017), and COPD (OR = 9.193, P = 0.005) independently predicted increased risk of ARDS in sepsis patients." (PMID 31257645, 2019). "Therefore, we characterized a novel THRIL/miR-19a/TNF-α pathway in sepsis." (PMID 32944003, 2020). "Therefore, THRIL is upregulated in sepsis and may sponge miR-19a to upregulate TNF-α, thereby promoting lung cell apoptosis." (PMID 32944003, 2020). "This might be due to that lnc‐THRIL facilitated inflammatory response by facilitating TNF‐α and other inflammatory markers, hence, aggravated the disease severity and increased the risk of ARDS, which eventually led to poor survival in sepsis patients." (PMID 31257645, 2019). "NEAT1, MALAT1, THRIL, XIST, MIAT and TUG1 are among lncRNAs that participate in the pathoetiology of sepsis-related complications." (PMID 34956235, 2021). "The expression levels of THRIL, miR-19a and TNF-α in plasma from sepsis patients (n = 66) and healthy controls (n = 66) were measured using RT-qPCR assay." (PMID 32944003, 2020). "Therefore, LPS-induced THRIL may participate in sepsis by inducing cell apoptosis." (PMID 32944003, 2020). "This study was therefore performed to investigate the interactions among THRIL, miR-19a and TNF-α in sepsis." (PMID 32944003, 2020). "Our data revealed that 29.4% of sepsis patients developed ARDS during hospitalization, and lnc‐THRIL was upregulated in sepsis patients developed ARDS with good value in distinguishing ARDS from non‐ARDS in sepsis patients." (PMID 31257645, 2019). "Lnc‐THRIL was upregulated in ARDS group compared with non‐ARDS group, and it had good value in distinguishing ARDS from non‐ARDS in sepsis patients (AUC: 0.706; 95%CI: 0.602‐0.809)." (PMID 31257645, 2019). "As for disease severity, lnc‐THRIL positively correlated with APACHE II score and SOFA score in sepsis patients." (PMID 31257645, 2019). "Our bioinformatics analysis showed that THRIL may interact with miR-19a, which targets TNF-α, a critical player in sepsis." (PMID 32944003, 2020). "This study mainly investigated the interactions among THRIL, miR-19a and TNF-α in sepsis." (PMID 32944003, 2020). "Additionally, sepsis patients were subdivided into ARDS group and non‐ARDS group, and correlations of lnc‐THRIL with disease severity in subgroups were determined." (PMID 31257645, 2019). "Spearman test illustrated that lnc‐THRIL relative expression was positively correlated with APACHE II score (r = 0.519, P < 0.001) and SOFA score (r = 0.393, P < 0.001) in sepsis patients." (PMID 31257645, 2019). "This might be attributed to that lnc‐THRIL might initiate the transcription of TNF‐α and thereby promote the inflammatory response in sepsis patients, which aggravated disease condition in sepsis patients." (PMID 31257645, 2019). "Lnc‐THRIL relative expression was positively correlated with levels of CRP (r = 0.421, P < 0.001), PCT (r = 0.251, P = 0.008), TNF‐α (r = 0.357, P < 0.001), and IL‐1β (r = 0.305, P = 0.001), but not correlated with IL‐17 level (r = −0.072, P = 0.459) in sepsis patients." (PMID 31257645, 2019). "Therefore, we were interested in whether lnc‐THRIL was involved in the pathogenesis of sepsis or not, and discovered that lnc‐THRIL was positively correlated with APACHE II score and SOFA score in sepsis patients." (PMID 31257645, 2019).
Kawasaki disease (5 papers, 2014 to 2020). A rare inflammatory disease characterized by an acute febrile, systemic, self-limiting, medium-vessel vasculitis primarily affecting children. "LincRNA1992 -THRIL is highly associated with Kawasaki disease and regulates immune responses through TNF-α37." (PMID 26725683, 2016). "The lincRNA THRIL, whose expression levels correlated with the severity of Kawasaki disease, induced expression of TNF-α by forming a ribonucleoprotein (RNP) complex with hnRNPL." (PMID 32929606, 2020). "In addition, THRIL expression was found to correlate with the severity of Kawasaki disease, an acute inflammatory disease of childhood, which also hinted the important roles of THRIL in inflammatory responses and inflammatory diseases." (PMID 29599646, 2018). "In 17 patients with Kawasaki disease, linc1992/THRIL expression was lower during acute phase of disease when TNFα levels are elevated, so linc1992/THRIL could be a new biomarker for immune activation." (PMID 25431574, 2014).
COVID-19 (3 papers, 2023 to 2025). A disease caused by infection with severe acute respiratory syndrome coronavirus 2. "THRIL is overexpressed in patients with COVID-19 and it can differentiate the acute phase of COVID-19." (PMID 37582734, 2023). "In addition, the expression level of THRIL was significantly upregulated in moderate and severe COVID-19 patients compared to the control group, with higher levels observed in severe patients." (PMID 40006907, 2025). "And similar to lncRNAs, ANRIL, THRIL, and NEAT1 are significantly upregulated in COVID-19 patients, suggesting their measurement could predict severity and improve clinical outcomes." (PMID 40144645, 2025).
lung carcinoma (3 papers, 2019 to 2023). "Besides, TUG1, FAS-AS1 and THRIL expression levels were fair diagnostic markers for lung cancer." (PMID 30866866, 2019). "In conclusion, THRIL improves the proliferation, migration, and apoptosis of lung cancer cells and inhibits apoptosis by down-regulating miR-99a." (PMID 37582734, 2023). "The results of flow cytometry indicated that the apoptosis rates of lung cancer A549 and H1299 cells in the si-THRIL group were raised (P < 0.001)." (PMID 37582734, 2023). "In this study, cell experiments confirmed that the expression of THRIL was significantly upregulated in lung cancer cell lines compared with that in BEAS-2B, which was basically consistent with the previous conclusion of our findings." (PMID 37582734, 2023). "In lung cancer cells, THRIL regulated IGF1R through miR-99a and then affected the proliferation, migration, invasion, and apoptosis." (PMID 37582734, 2023). "Although the underlying mechanism of this observation is not clear, this result is in accordance with a recently reported sex-specific role of THRIL in lung cancer." (PMID 32426538, 2020). "The survival rate of A549 and H1299 cells of lung cancer in the si-THRIL group decreased (B and P < 0.001), supporting that THRIL could accelerate the proliferation of lung cancer cell lines." (PMID 37582734, 2023). "THRIL might reduce its pro-tumor activity by competitively binding to miR-99a, thereby affecting the proliferation, migration, and invasion of lung cancer cells and ameliorating apoptosis." (PMID 37582734, 2023). "Additionally, the role of THRIL in the regulation of miR-99a in lung cancer and its mechanism were elucidated." (PMID 37582734, 2023). "After the downregulation of THRIL expression, the proliferation, migration, and invasion activities of A549 and H1299 cells were reduced and the apoptosis was raised, indicating that THRIL may play a role in the carcinogenesis and development of lung cancer." (PMID 37582734, 2023). "Conclusively, IGF1R might participate in the regulation of the THRIL/miR-99a axis in the lung carcinoma cell line." (PMID 37582734, 2023). "The expression of THRIL was upregulated and miR-99a was downregulated in lung cancer cells." (PMID 37582734, 2023). "THRIL/ miR-99a/IGF1R axis might be a novel potential target in lung cancer." (PMID 37582734, 2023). "THRIL can regulate the expression of IGF1R through miR-99a, thereby promoting the growth of lung cancer cells and inhibiting apoptosis." (PMID 37582734, 2023). "Compared with BEAS-2B, the level of THRIL in lung cancer cells H1299, HCC827, A549, PC9, H526, and DMS273 increased prominently (P < 0.001), elucidating abnormal expression of THRIL in lung cancer." (PMID 37582734, 2023).
autism (2 papers, 2017 to 2024). Persistent deficits in social interaction and communication and interaction as well as a markedly restricted repertoire of activity and interest as well as repetitive patterns of behavior. "Our results provide further support for altered innate immunity being an important autism pathogenic factor, with autistic children showing increased blood TNF-α concentrations associated with symptom severity, and decreased expression of the THRIL gene involved in regulating TNF-α." (PMID 29137272, 2017).
coronary heart disease (2 papers, 2020 to 2022). "For instance, serum lncRNA-AWPPH is an independent risk factor for coronary artery disease and lncRNA THRIL is positively related to the accumulating rate of major adverse cardiovascular events in patients with coronary heart disease." (PMID 35538435, 2022). "Here in this study, the role and interactions of lncRNA THRIL, AKT pathway and FUS in the development of coronary heart disease were investigated." (PMID 32907536, 2020).
Hyperglycemia (2 papers, 2018 to 2021). An increased concentration of glucose in the blood. "Our study provides the first preliminary evidence that expression of the long non-coding RNAs, THRIL, and SALRNA1 were decreased in patients with type 2 diabetes and negatively correlated with hyperglycemia, senescence, and inflammation." (PMID 30139387, 2018).
multiple sclerosis (2 papers, 2019 to 2021). A progressive autoimmune disorder affecting the central nervous system resulting in demyelination. "In multiple sclerosis patients, THRIL has been closely related with Fas cell surface death receptor-antisense 1 (FAS-AS1), playing a key role in the regulation of immune responses." (PMID 33675584, 2021).
osteosarcoma (2 papers, 2021 to 2023). A usually aggressive malignant bone-forming mesenchymal neoplasm, predominantly affecting adolescents and young adults. "In osteosarcoma, the expression of THRIL is enhanced in patients and is correlated with the pathogenesis of this tumor, indicating its function as a biomarker in osteosarcoma monitoring." (PMID 37582734, 2023). "LncRNA THRIL has also been shown to regulate TNF-α expression and participate in immune response in osteosarcoma." (PMID 34692688, 2021). "LncRNA THRIL has been shown to regulate TNF-α expression and participate in immune response in osteosarcoma." (PMID 34692688, 2021).
schizophrenia (2 papers, 2021 to 2025). A major psychotic disorder characterized by abnormalities in the perception or expression of reality. "While Gomafu, PINT, GAS5, TCONS_l2_00021339, IFNG-AS1, FAS-AS1, PVT1, and TUG1 are among down-regulated lncRNAs in schizophrenia, MEG3, THRIL, HOXA-AS2, Linc-ROR, SPRY4-IT1, UCA1, and MALAT1 have been up-regulated in these patients." (PMID 34220567, 2021).
viral infection (2 papers, 2019 to 2025). "The innate immune system acts as the primary line of defense against viral infections, and elucidating THRIL’s role in modulating this response is critical for understanding the dynamics of virus–host interactions." (PMID 40006907, 2025). "Collectively, these findings suggest that THRIL exerts a suppressive effect on interferon regulation following viral infection." (PMID 40006907, 2025). "Collectively, these results indicate that THRIL expression is negatively regulated in response to both RNA and DNA viral infections within A549 cells, underscoring its potential role in host antiviral defense mechanisms." (PMID 40006907, 2025). "It is well established that poly (I:C) serves as a potent inducer of interferons; thus, we further examined whether the downregulation of THRIL during viral infection correlated with elevated levels of type I and type III interferons." (PMID 40006907, 2025). "The lncRNAs THRIL, NeST, NEAT, and lincRNA-Cox2 can participate in immune responses against viral infection mainly through regulating the expression of TNF-α, IFN-γ, IL8, and inflammatory response, respectively." (PMID 32063887, 2019).
cerebral infarction (1 paper, 2021). An ischemic condition of the brain, producing a persistent focal neurological deficit in the area of distribution of the cerebral arteries. "Brain region 2,3,5-Triphenyltetrazolium (TTC) staining and quantitative analysis of cerebral infarction volume, RT-qPCR, and fluorescence immunostaining were performed for assessing THRIL expression." (PMID 33675584, 2021).
Cerebral ischemia (1 paper, 2021). Restriction of arterial blood supply to the brain associated with insufficient oxygenation to support the metabolic requirements of the tissue. "Our study demonstrates that THRIL can aggravate cerebral ischemia-reperfusion injury by competitively binding to miR-24-3p to promote the upregulation of NRP1 expression and further promote the activation of the NF-κB p65 signaling pathway." (PMID 33675584, 2021). "Based on the role of THRIL in inflammation-related diseases, we first studied the role of THRIL in cerebral ischemia-reperfusion injury." (PMID 33675584, 2021). "Our aim of this study was to investigate the role and the molecular mechanism of THRIL in cerebral ischemia-reperfusion injury." (PMID 33675584, 2021). "We demonstrated that THRIL was upregulated in both in vitro and in vivo models of brain ischemia-reperfusion injury." (PMID 33675584, 2021). "Through our preliminary experiments, we found that THRIL was up-regulated in vitro and in vivo models of brain ischemia-reperfusion injury." (PMID 33675584, 2021). "Similar results were obtained in this study, where THRIL was upregulated in models of brain ischemia-reperfusion injury, which was closely related to OGD/R-induced inflammation." (PMID 33675584, 2021). "In this study, we first investigated the role of THRIL in cerebral ischemia-reperfusion injury." (PMID 33675584, 2021). "Thus, we focused on the role of THRIL in the apoptosis and inflammation during the the cerebral ischemia-reperfusion injury." (PMID 33675584, 2021). "In conclusion, THRIL could aggravate cerebral ischemia-reperfusion injury by competitively binding to miR-24-3p to promote the upregulation of NRP1 and further promote the activation of the NF-κB p65 signaling pathway." (PMID 33675584, 2021). "Therefore, THRIL may be a novel target for the prediction and treatment of cerebral ischemia-reperfusion injury." (PMID 33675584, 2021). "Thus, THRIL aggravates cerebral ischemia-reperfusion injury." (PMID 33675584, 2021). "Therefore, THRIL might improve brain ischemia-reperfusion injury by participating in inflammation." (PMID 33675584, 2021).
chronic obstructive pulmonary disease (1 paper, 2019). A chronic and progressive lung disorder characterized by the loss of elasticity of the bronchial tree and the air sacs, destruction of the air sacs wall, thickening of the bronchial wall, and mucous accumulation in the bronchial tree. "Besides, lnc‐THRIL, smoke, and chronic obstructive pulmonary disease independently predicted increased risk of ARDS." (PMID 31257645, 2019).
coronary artery stenosis (1 paper, 2023). "The upregulation of THRIL has been observed in CHD and is correlated with enhanced coronary stenosis, systemic inflammation, and MACEs." (PMID 37238718, 2023). "The results revealed an expression signature consisting of the upregulation of RMRP (p < 0.01) and downregulations of THRIL (p < 0.01) and HIF1A (p < 0.01) among patients with a positive thallium stress test and no significant coronary artery stenosis within 6 months after baseline treatment." (PMID 37238718, 2023).